IL1RN (interleukin 1 receptor antagonist)
Diseases named in the same sentence as IL1RN in open-access papers (continued):
Sharing a sentence is not in itself a finding about the gene and the disease.
endometriosis (5 papers, 2021 to 2025). The growth of functional endometrial tissue in anatomic sites outside the uterine body. "Although Wen suggests an approximate 3.5-fold increased risk for Chinese women with endometriosis carrying the IL1RN*2-allele, we found this allele protective in Mexican women (except for endometriosis stage IV)." (PMID 36028805, 2022). "Nevertheless, the highest frequency of the IL1RN*2-allele homozygote genotype (25%) was observed again in endometriosis stage IV." (PMID 36028805, 2022). "Women with endometriosis stage IV (severe) had frequencies more alike to the CTR group in the IL1RN*2 allele frequency (31.2% vs. 27.2%) and carriage rate (37.5% vs. 41.9%)." (PMID 36028805, 2022). "Like Hsieh and Wen, we found the IL1RN*1/IL1RN*2-allele heterozygote in approximately 10% of women with endometriosis." (PMID 36028805, 2022). "Endometriosis‐associated M2 macrophages also express IL1A/B antagonist IL1RN, which may also contribute to fine‐tuning of IL1 signaling and risk conferred by variants at this locus." (PMID 40938538, 2025). "The IL1RN variable number tandem repeat (VNTR) polymorphism has been associated with altered levels of IL-1RA and susceptibility to endometriosis." (PMID 39767772, 2024). "The IL1RN*1/IL1RN*3 and IL1RN*1/IL1RN*4 genotypes showed very low frequencies (< 6%) and carriage rate (*1*3 + *1*4; < 10%) in both groups and in all four stages of endometriosis." (PMID 36028805, 2022). "When we analyzed the IL1RN*2-allele frequency according to rASRM staging, all endometriosis stages showed statistical difference when compared to the CTR group, except for endometriosis stage IV (p > 0.05)." (PMID 36028805, 2022). "Surprisingly, we observed a higher frequency of IL1RN*1 in women with endometriosis and a higher frequency of IL1RN*2 in the CTR group, which was statistically different (p < 0.0008)." (PMID 36028805, 2022). "When we analyze the carriage rate of IL1RN*2-allele (*1*2 + *2*2), the ENDO group and the four stages of endometriosis had lower frequencies than the CTR group." (PMID 36028805, 2022). "We do not know the biological meaning of a low frequency of IL1RN*2 allele and homozygote genotype in women with endometriosis." (PMID 36028805, 2022). "Surprisingly, we found the highest prevalence of the IL1RN*2-allele homozygote genotype (10% vs. 1%) and the IL1RN*2-allele in Mexican women with (18% vs. < 7%) and without endometriosis (27% vs. < 4%)." (PMID 36028805, 2022). "Unlike them, who found IL1RN*1-allele homozygote in more than 84% and 92% of women with and without endometriosis, we observed it in 70% and 48%, respectively." (PMID 36028805, 2022). "The most common alleles were IL1RN*1 (68% and 80% in women without and with endometriosis, respectively) and IL1RN*2 (27% and 18% in women without and with endometriosis, respectively), as reported in the literature." (PMID 36028805, 2022). "Moreover, cyto-hub gene analysis revealed that CSNK2A1, CSNK2A2, TOP1, PRKACA, RBM39 (plasma), ALB, ACTB, GAPDH, FN1, APOA1 (serum), S100-A9, CXCL1, IL1RN, CSTA, S100-A8 (menstrual blood) and THBS1, ALB, CD44, ANXA2, and LUM (urine) were the top 5 proteins expressed in women with endometriosis." (PMID 39061077, 2024).
keratoconus (5 papers, 2008 to 2025). A degenerative, structural disorder of the eye, characterized by a cone-shaped protrusion of the cornea. "The goal of this study was to elucidate whether polymorphisms in IL1A, IL1B, and IL1RN are associated with keratoconus in Korean patients." (PMID 19043479, 2008). "Moreover, in ImCs within the corneal stroma, increased expression of IL23A and CXCL1 and decreased expression of the anti-inflammatory gene IL1RN further confirmed the important role of inflammation and immune regulation in keratoconus progression." (PMID 40426861, 2025). "We investigated the association between IL1A (rs1800587, rs2071376, and rs17561), IL1B (rs1143627, rs16944, rs1143634, and rs1143633), and IL1RN (rs419598, rs423904, rs424078, and rs315952, variable number tandem repeat [VNTR]) polymorphisms in 100 unrelated Korean keratoconus patients." (PMID 19043479, 2008).
Bladder Cancer (4 papers, 2014 to 2024). "The expression of IL1RN is negatively associated with bladder cancer cell proliferation." (PMID 36292719, 2022). "IL1RN, which serves as a natural interleukin-1 receptor antagonist, is negatively correlated with the proliferation of bladder cancer cells." (PMID 39445019, 2024). "We show that low IL1RN mRNA levels correlate with increased migration and tissue invasion capacities of bladder cancer cell lines." (PMID 34070905, 2021). "Furthermore, polymorphisms in the IL1RN gene were associated with recurrence after BCG immunotherapy and susceptibility to bladder cancer." (PMID 34070905, 2021). "Conversely, IL1RN mRNA levels were higher in semi-benign UROtsa and non-invasive RT4 cell lines as well as in primary epithelial cells derived from apparently healthy ureter tissue, supporting the idea that IL1RA may impair invasiveness of bladder cancer cells." (PMID 34070905, 2021).
colitis (4 papers, 2021 to 2025). Inflammation of the colon. "Knockout studies have shown that Il1rn-deficient mice spontaneously develop colitis with high mortality." (PMID 40963602, 2025). "CNVs on IL1RN were significantly linked to IRAE in general and associated with all three main IRAE in particular, i.e., colitis, hepatitis and pancreatitis." (PMID 35053465, 2022). "CNVs on IKZF1, FAN1 and IL1RN were linked to IRAE, colitis, hepatitis or pancreatitis." (PMID 35053465, 2022). "The phenotype named Colitis contains seven DEGs from our lists: IL10, IL11, IL1B, IL1RN, IL6, MIF and TNF." (PMID 34680872, 2021).
gout (4 papers, 2021 to 2025). A condition characterized by painful swelling of the joints, which is caused by deposition of urate crystals. "In eQTL analysis, rs9973741 (allele G, which is the risk allele for gout) associated with decreased expression of IL1RN in the prostate and decreased expression of both IL1RN and IL1R1 in whole blood, while increasing IL1RN expression in the testes." (PMID 40385401, 2025).
Hepatitis (4 papers, 2008 to 2024). Inflammation of the liver. "CNVs on IL1RN and deletions on PRDM1 were significantly linked to IRAE, whereas duplications on CD274 and CNVs on SLCO1B1 were significantly linked to hepatitis." (PMID 35053465, 2022). "Proteins that uniquely distinguish HCC patients with low AFP from patients with hepatitis include IL1RN, IFNG, CDKN1A, RETN, CXCL14, and FGF2." (PMID 19578489, 2008). "Importantly, we also identified 8 proteins that significantly differentiate HCC patients with ‘normal’ levels of AFP (< 20 ng/ml) from hepatitis patients (p < 0.05) (IL1RN, IFNG, CDKN1A, RETN, CXCL14, CTNNB, FGF2, and SELL)." (PMID 19578489, 2008). "Regarding CNVs, significant markers included PRDM1 deletions and IL1RN (IRAE), CD274 duplications and SLCO1B1 (hepatitis), PRDM1 and CD274 (encephalitis), and PRDM1, CD274, TSHR, and FAN1 (myositis)." (PMID 35053465, 2022).
Insulin resistance (4 papers, 2011 to 2025). Increased resistance towards insulin, that is, diminished effectiveness of insulin in reducing blood glucose levels. "IL1F10/IL-38 and IL1RN variants (rs6759676 and rs4251961) in partial LD with the lead SNP (r2LD:0.10 and 0.61) have been recently reported to be protective against the development of insulin resistance." (PMID 33517400, 2021). "Specifically, they showed elevated IL1RN (a marker of systemic inflammation), ANGPTL4 (a key regulator of lipid metabolism), DCBLD2 (associated with insulin resistance), and LEP (a hormone for long-term energy balance)." (PMID 40528258, 2025). "We found clear evidence that signals for IL-1β, IL1RN, TNF-α and TGFβ-1 are present in both adipose and liver tissues and that these are linked to the development of inflammation and insulin resistance in the HFC-fed mice." (PMID 21410952, 2011). "This suggests that IL1RN-mediated inhibition of IL-1 signaling may contribute to metabolic disturbances, potentially exacerbating insulin resistance and systemic inflammation." (PMID 40181376, 2025).
knee osteoarthritis (4 papers, 2020 to 2024). "In these studies, we examined the association of single nucleotide polymorphisms (SNPs) of the IL1RN gene with radiographic severity of symptomatic knee osteoarthritis (SKOA) and the risk of incident OA." (PMID 31852669, 2020).
Majeed syndrome (4 papers, 2020 to 2025). Majeed syndrome is a rare genetic multisystemic disorder characterized by the triad of chronic recurrent multifocal osteomyelitis, congenital dyserythropoietic anemia, and variable transient inflammatory dermatosis. "Majeed syndrome and deficiency of the interleukin-1 receptor antagonist (DIRA) are monogenic ABDs that result from homozygous mutations in the disease-associated gene." (PMID 37342528, 2023). "Interestingly a CRMO-like presentation is also seen in SAPHO (synovitis, acne, pustulosis, hyperostosis and osteitis) and in the monogenic mimics Majeed Syndrome (LPIN2 mutation) and Deficiency of Interleukin-1 Receptor Antagonist Syndrome (IL1RN mutation)." (PMID 41008692, 2025). "However, certain syndromic forms of CNO, like Majeed syndrome and deficiency of the IL-1 receptor antagonist (DIRA), have been linked to specific gene mutations (LPIN2 and IL1RN), shedding light on the role of IL-1β in inflammation." (PMID 38137947, 2023).
Oral Squamous Cell Carcinoma (4 papers, 2020 to 2026). "On the other hand, a recent study reported that IL-1RN is significantly underexpressed in oral squamous cell carcinomas (OSCCs) compared to normal tissues." (PMID 39766795, 2024). "In contrast to these findings, IL1RN exhibited low expression in oral squamous cell carcinomas (OSCCs)." (PMID 33238942, 2020).
pancreatic cancer (4 papers, 2020 to 2026). "To study the biological function of IL-1Ra in tumors, we generated a set of mouse pancreatic cancer cell lines with a knockout (KO) of the Il1rn gene, encoding IL-1Ra, and compared the tumor growth rates in immune-competent and immune-deficient mice." (PMID 37563620, 2023). "IL1RN is expected to become a novel target for pancreatic cancer immunotherapy, providing experimental evidence for the stratified treatment of PC." (PMID 42164145, 2026).
pulmonary fibrosis (4 papers, 2017 to 2023). Chronic progressive interstitial lung disorder characterized by the replacement of the lung tissue by connective tissue, leading to progressive dyspnea, respiratory failure, or right heart failure. "Furthermore, our group has previously shown that prophylactic administration of BMMCs reduced mRNA levels of TGF-β, IL-1β, IL-1α, and IL-1RN and attenuated silica-induced lung fibrosis." (PMID 29126438, 2017).
thoracic aortic aneurysm (4 papers, 2022 to 2025). An aneurysm formed in the wall of the proximal portion of the descending aorta proceeding from the arch of the aorta. "Another study reported an Il1rn+/Trem1+ macrophage subpopulation in thoracic aortic aneurysm and dissection, and Il1rn and Trem1 were also relatively highly expressed in the Mac_TREM2 subtype we found." (PMID 40463378, 2025). "Recently, an Il1rn+/Trem1+ macrophage subpopulation was identified as a cellular target for mitigating the progression of thoracic aortic aneurysm and dissection by using scRNA‐seq." (PMID 39720896, 2024).
viral infection (4 papers, 2019 to 2026). "Previous experiments have shown viral infections can inhibit C3 complement production, and that the loss of IL1RN can enhance susceptibility to viral infections, which may suggest an interaction between dietary olive oil, the host and the virome." (PMID 30781503, 2019).
Gastric Diseases (3 papers, 2018 to 2019). "Recently, the polymorphism of proinflammatory cytokines such as IL1RN and anti-inflammatory cytokines such as IL-10 has been implicated in clarifying host factors in the development of gastric diseases." (PMID 31885568, 2019).
inflammatory bowel disease (3 papers, 2018 to 2025). A spectrum of small and large bowel inflammatory diseases of unknown etiology. "Among these patients, one had a co-manifestation of inflammatory bowel disease, while another carried a heterozygous variant of unknown significance in the IL1RN gene." (PMID 40361097, 2025).
influenza (3 papers, 2014 to 2022). An acute viral infection of the respiratory tract, occurring in isolated cases, in epidemics, or in pandemics; it is caused by serologically different strains of viruses (influenzaviruses) designated A, B, and C, has a 3-day incubation period, and usually lasts for 3 to 10 days. "Rsad2, Cxcl10, Saa3, Irf7, and Il1rn, which have been reported in influenza, whereas the role of LCN2 in influenza was still unknown." (PMID 35495713, 2022).
malaria (3 papers, 2005 to 2020). Malaria is a serious and sometimes fatal disease caused by a parasite that commonly infects a certain type of mosquito which feeds on humans. "In this way, IL18R and IL1RN that encode for receptors of pro-inflammatory cytokines were up-regulated in malaria patients in Benin and in CM patients in our study population, whereas IL18R was up-regulated in blood from CM mice." (PMID 31666081, 2019). "In Thai malaria patients, the population frequencies of the -31C and -31T alleles were nearly equal, and allele 4 (with four repeats) was predominant in the IL1RN VNTR polymorphism." (PMID 16098232, 2005). "Predicted inhibited upstream regulators of monocyte gene expression in subpatent primary infection included MAPK1, IL1RN and TRIM24, which overlapped with regulators predicted to be inhibited in malaria‐naive volunteers experiencing symptomatic malaria following P. falciparum sporozoite infection." (PMID 32566226, 2020).
melanoma (3 papers, 2020 to 2025). A malignant, usually aggressive tumor composed of atypical, neoplastic melanocytes. "A study analyzing 95 melanoma patients treated with ICIs found that genes affected by VARs associated with hypophysitis include SMAD3, PRDM1, and IL1RN, while genes affected by CNVs related to the occurrence of hypophysitis are TERT, SMAD3, JAK2, PRDM1, FAN1, CD274, and UNG." (PMID 41465179, 2025).
osteomyelitis (3 papers, 2021 to 2024). An acute or chronic inflammation of the bone and its structures due to infection with pyogenic bacteria. "Furthermore, their study revealed that individuals harboring the IL1RN*2/*2 + IL1B-511T/T polymorphism genotype were all afflicted with osteomyelitis." (PMID 39301021, 2024).
pancreatitis (3 papers, 2019 to 2024). Inflammation of the pancreas. "The importance of pro-inflammatory cytokines in pancreatitis has been highlighted by a recent study in 84 patients with AP who were screened for known polymorphisms in TNFα, interleukin 1 (IL-1), IL-1 receptor antagonist (IL1RN), IL-6, and IL-10." (PMID 30681551, 2019).
pneumonia (3 papers, 2017 to 2024). An acute, acute and chronic, or chronic inflammation focally or diffusely affecting the lung parenchyma, caused by an infection in one or both of the lungs (by bacteria, viruses, fungi, or mycoplasma.). "IL1RN and IL1b were also significantly upregulated interleukin genes in pneumonia cases, which were consistent with the increased expression of plasma IL-1Ra and IL-1b proteins." (PMID 36119044, 2022). "Consistent with the previous findings, we found that levels of a variety of cytokines, such as IL-6, IL-1RN, and TNF-α, increased rapidly in the pneumonia cases, thereby accelerating the inflammatory response." (PMID 36119044, 2022).
schizophrenia (3 papers, 2022 to 2025). A major psychotic disorder characterized by abnormalities in the perception or expression of reality. "Previous research identified IL1RN, a protein that binds to IL‐1 receptors, as a useful marker for evaluating susceptibility to Tourette's syndrome, schizophrenia, and the postnatal development of the brain." (PMID 40237232, 2025). "Shirts B.H., Wood J., Yolken R.H., Nimgaonkar V.L. Association studyof IL10, IL1β, and IL1RN and schizophrenia using tag SNPs froma comprehensive database: suggestive association with rs16944 atIL1β." (PMID 38988763, 2024). "Thereis a tendency for the association of the GAGG haplotype(rs1143627, rs16944, rs1143623, rs4848306) of the ILBgene; TG haplotypes (rs315952, rs9005) and TT61 rs5254(rs4) of IL1RN, and CT haplotype (rs4251961, rs419598) inIL1RN with the risk of schizophrenia." (PMID 38988763, 2024).
thyroid cancer (3 papers, 2020 to 2024). "IL1RN polymorphisms have similarly been proven to reduce the population risk of thyroid cancer risk." (PMID 36483329, 2022). "They measured preoperative IL1RN serum levels of patients with thyroid cancer, and the results showed that the serum concentrations of sIL-1ra were significantly higher in anaplastic carcinoma (ATC) and follicular carcinoma (FTC) patients." (PMID 33238942, 2020). "IL1RN was a good prognostic and diagnostic biomarker for PTC and might promote thyroid cancer progression through immune-related pathways." (PMID 39497824, 2024). "Niedzwiecki, S. and colleagues assayed the serum levels of IL1RN in thyroid cancer patients." (PMID 33238942, 2020). "IL1RN may promote thyroid cancer progression through immune-related pathways." (PMID 33238942, 2020).